NUCB1 (nucleobindin 1)
Description:
Major calcium-binding protein of the Golgi which may have a role in calcium homeostasis (By similarity). Acts as a non-receptor guanine nucleotide exchange factor which binds to and activates alpha subunits of guanine nucleotide-binding proteins (G proteins) (By similarity).
Synonyms: NUC; Calnuc
Tractability: Antibody: UniProt places it where antibodies can reach, with medium confidence; UniProt predicts a signal peptide or a membrane-spanning region; its Gene Ontology location is reachable by antibodies, with medium confidence. PROTAC: ubiquitination databases record sites on it; its protein half-life has been measured.
Gene: Protein-coding gene on chromosome 19 (48,900,050 to 48,923,473, forward strand). Ensembl gene ENSG00000104805.
Subcellular location: Golgi apparatus, cis-Golgi network membrane; Cytoplasm; Secreted
Subcellular location (Human Protein Atlas): Golgi apparatus; Microtubules; Vesicles; Predicted to be secreted
Pathways (Reactome):
Metabolism of proteins: Post-translational protein phosphorylation; Regulation of Insulin-like Growth Factor (IGF) transport and uptake by Insulin-like Growth Factor Binding Proteins (IGFBPs)
Gene Ontology:
Molecular function: protein binding; calcium ion binding; G-protein alpha-subunit binding; guanyl-nucleotide exchange factor activity
Biological process: small GTPase-mediated signal transduction
Cellular component: endoplasmic reticulum-Golgi intermediate compartment; extracellular exosome; extracellular region; Golgi apparatus; membrane; cytoplasm; endoplasmic reticulum lumen; endomembrane system
Genetic constraint (gnomAD): Loss-of-function variants: 46 observed, 58.6 expected, observed/expected ratio (o/e) 0.79, 90% interval 0.62 to 1. The upper end of that interval is the gene's LOEUF score, 1, which puts it in group 4 of 6, group 1 being the genes least tolerant of losing a copy. Missense variants: 568 observed, 613.92 expected, observed/expected ratio (o/e) 0.93, 90% interval 0.86 to 0.99. Synonymous variants: 228 observed, 247.42 expected, observed/expected ratio (o/e) 0.92, 90% interval 0.83 to 1.03.
Homologues: Orthologues: chimpanzee NUCB1 (99% identical), macaque NUCB1 (98% identical), dog NUCB1 (92% identical), pig NUCB1 (88% identical), guinea pig NUCB1 (88% identical), mouse Nucb1 (88% identical), rat Nucb1 (87% identical), rabbit NUCB1 (79% identical), tropical clawed frog nucb1 (66% identical), zebrafish nucb1 (60% identical), Drosophila melanogaster NUCB1 (39% identical), Caenorhabditis elegans nucb-1 (33% identical). Paralogues in human: NUCB2 (55% identical).
Diseases named in the same sentence as NUCB1 in open-access papers:
NUCB1 is named in the same sentence as 38 diseases in open-access papers, as found by Europe PMC text mining. Sharing a sentence is not in itself a finding about the gene and the disease. The quoted sentences say what the papers report.
pancreatic cancer (4 papers, 2021 to 2023). "The upregulation of NUCB1 worked in synergy with gemcitabine and impaired pancreatic cancer cell proliferation." (PMID 36977668, 2023). "METTL3-m6A-YTHDF2-mediated decay of nucleobindin 1 (NUCB1) mRNA counteracts the effects of NUCB1 in halting pancreatic cancer growth and augmenting the antitumor with gemcitabine (GEM)." (PMID 36999016, 2023). "Taken together, our study revealed crucial functions of NUCB1 in suppressing proliferation and enhancing the effects of gemcitabine in pancreatic cancer cells and identified METTL3-mediated m6A modification as a mechanism for NUCB1 downregulation in PDAC." (PMID 33855021, 2021). "Functionally, NUCB1 overexpression suppressed proliferation and enhanced the effects of gemcitabine in pancreatic cancer cells in vitro and in vivo." (PMID 33855021, 2021). "Functionally, NUCB1 overexpression suppressed pancreatic cancer cell proliferation and showed additive effects with gemcitabine (GEM) in vitro and in vivo." (PMID 33855021, 2021). "One important clinical implication of our findings relates to the role of NUCB1 in enhancing the anti-tumor effects of gemcitabine, a first-line chemotherapy for pancreatic cancer patients." (PMID 33855021, 2021). "In this study, we provided evidence for a role of NUCB1 in regulating proliferation and the anti-tumor effects of gemcitabine in pancreatic cancer cells, and proposed a mechanism whereby METTL3 controls NUCB1 expression, which then modulates ATF activity and subsequently controls the UPR." (PMID 33855021, 2021). "The additive effects of NUCB1 with gemcitabine in pancreatic cancer cells suggest that targeting NUCB1, in combination with other current treatment strategies, may improve therapeutic efficacy and clinical outcomes for PDAC patients." (PMID 33855021, 2021). "We next determined whether NUCB1-affected pancreatic cancer cell proliferation." (PMID 33855021, 2021). "We used two pancreatic cancer cell lines, SW1990 and CFPAC1, which relatively express lower levels of NUCB1 compared to HPDE, a normal pancreatic duct epithelial cell line, to generate stable cells with overexpression of NUCB1 or control vector." (PMID 33855021, 2021). "Collectively, these data reinforce that NUCB1 suppresses proliferation and enhances the anti-tumor effects of GEM in pancreatic cancer cells in vivo." (PMID 33855021, 2021). "Finally, how NUCB1 contributes to PDAC cancer progression, as well as the mechanism through which it influences the anti-tumor effects of gemcitabine in pancreatic cancer cells, have yet to be elucidated." (PMID 33855021, 2021).
Alzheimer disease (3 papers, 2015 to 2021). A progressive, neurodegenerative disease characterized by loss of function and death of nerve cells in several areas of the brain leading to loss of cognitive function such as memory and language. "Furthermore, NUCB1 was reported as a novel pan-neuronal calcium handling marker, correlated to Alzheimer’s disease." (PMID 34769107, 2021).
breast carcinoma (3 papers, 2022 to 2024). "In contrast to the effect of NUCB1 in colon cancer and breast cancer, NUCB1 suppressed the cell growth and promoted the apoptosis of PC cells both in vitro and in vivo, while loss of NUCB1 in turn promoted PC cell growth and inhibited cell apoptosis." (PMID 35936737, 2022). "Currently, an oncogenic role of NUCB1 has been found in colon cancer and breast cancer." (PMID 35936737, 2022). "Two others, NUCB1 [OR: 5.65, 95% CI: 2.64 to 12.09; PP4: 0.98] and FGFR3 [OR: 2.54, 95% CI: 1.77 to 3.66; PP4: 0.99] were both associated with a higher risk of bladder cancer and were observed to have associations with other cancers, including luminal B breast cancer and lung adenocarcinoma." (PMID 38684708, 2024). "Nucleobindin-1, a soluble factor upregulated in the coculture model, was recently shown to be essential for matrix metalloproteinase (MMP) trafficking, through which it is able to regulate matrix degradation and the invasive ability of breast cancer cells." (PMID 35292627, 2022).
colon cancer (3 papers, 2015 to 2023). "Sorcin is associated with multidrug-resistance in human leukemia cells and nucleobindin 1 is evaluated as a biomarker of colon cancer." (PMID 25872475, 2015).
pancreatic ductal adenocarcinoma (3 papers, 2021 to 2023). An infiltrating adenocarcinoma that arises from the epithelial cells of the pancreas. "Although it has been demonstrated that NUCB1 overexpression helps tumor progression, a 5-year follow-up study showed the worst prognosis for pancreatic ductal adenocarcinoma (PDAC) patients with low levels of NUCB1." (PMID 36611989, 2023). "Previous reports have shown that the downregulation of NUCB1 in pancreatic ductal adenocarcinoma indicates poor prognosis, and the N-terminal DNA-binding domain of NUCB1 can bind to canonical E-box sequences and induce cell epithelial–mesenchymal transition." (PMID 37007952, 2023). "Correlations between NUCB1 expression and clinicopathologic features in patients with pancreatic ductal adenocarcinoma." (PMID 33855021, 2021).
systemic lupus erythematosus (3 papers, 2023). An autoimmune multi-organ disease typically associated with vasculopathy and autoantibody production. "NUCB1 presence has been detected in the supernatant of a murine B-cell line with systemic lupus erythematosus." (PMID 36611989, 2023). "NUCB1 was first discovered in systemic lupus erythematosus (SLE), which bound to nucleosome ladder DNA to induce autoimmunity and thymus apoptosis." (PMID 37547718, 2023). "Nucleobindin1 (NUCB1) was first identified in systemic lupus erythematosus (SLE) and was characterized by a variety of functional binding domains, including DNA binding domains, nuclear localization signals, etc., which gave it many functions (Sinha, Pattnaik & Aradhyam, 2019)." (PMID 37547718, 2023). "The increase in serum levels of NUCB1 in lupus-prone mice became known almost 30 years ago." (PMID 37047165, 2023). "NUCB1 was first found in the supernatant of a B lymphocyte cell line from systemic lupus erythematosus (SLE)-prone mice." (PMID 37047165, 2023).
colorectal cancer (2 papers, 2023). A primary or metastatic malignant neoplasm that affects the colon or rectum. "Similar to NHL, in colorectal cancer, high expression levels of NUCB1 showed an association with shorter PFS and OS." (PMID 36611989, 2023). "The expression of COX-2 and NUCB1 in colorectal cancer was predicted using the Human Protein Atlas (HPA)." (PMID 37547718, 2023). "Through bioinformatics, NUCB1 in colorectal cancer tissues was reduced compared to normal tissue, both at the mRNA and protein levels." (PMID 37547718, 2023). "Next, we will continue to improve cell experiments to further demonstrate the expression and function of NUCB1 in colorectal cancer cells, and explore whether the combination of NUCB1 and COX-2 induces bevacizumab resistance." (PMID 37547718, 2023). "The higher the differentiation degree of colorectal cancer, the higher the positive rate of NUCB1, indicating that NUCB1 may be involved in the differentiation of colorectal cancer." (PMID 37547718, 2023). "In colorectal cancer, COX-2 and NUCB1 expression were significantly correlated (rs = 0.6312, P < 0.001)." (PMID 37547718, 2023). "It is rational to speculate that the combination of NUCB1 and COX-2 induces the progression of colorectal cancer." (PMID 37547718, 2023). "In addition, NUCB1 was significantly relevant to TNM stage, differentiation degree, and lymphatic metastases, suggesting that NUCB1 may induce the proliferation and metastasis of colorectal cancer." (PMID 37547718, 2023).
type 2 diabetes (2 papers, 2017 to 2024). "The downregulated NUCB1 in our COVID-19 patients suggested a harmful effect related to type 2 diabetes as it performs amyloid stabilization in human islet cells to prevent fibrils in the pancreas that impact type 2 diabetes." (PMID 38760690, 2024).
adenoma (1 paper, 2024). A neoplasm arising from the epithelium. "Evaluating the similarities of significantly over-represented proteins in the adenoma and carcinoma cell lines, 226 proteins were identified, of which the most over-represented included proteins involved in signal transduction (NUCB1, ZYK) and apoptosis (RIPK3, CASP8)." (PMID 39462388, 2024).
bladder cancer (1 paper, 2024). "NUCB1, GSTM4, and FGFR3 had associations with bladder cancer risk." (PMID 38684708, 2024).
cervical cancer (1 paper, 2023). A primary or metastatic malignant neoplasm involving the cervix. "Among the multiple proteins secreted by cervical cancer cells, four upregulated proteins were identified: nucleobindin-1 (NUCB1), carboxypeptidase E (CPE), calreticulin (CALR), and heat-shock protein beta-1 (HSPB1)." (PMID 36992411, 2023).
colorectal adenocarcinoma (1 paper, 2023). The most common type of colorectal carcinoma. "Both COX-2 and NUCB1 are overexpressed and significantly associated in colorectal adenocarcinoma." (PMID 37547718, 2023). "According to the UALCAN and HPA database, COX-2 was upregulated while NUCB1 was downregulated in colorectal adenocarcinoma, both at the protein and gene levels." (PMID 37547718, 2023). "Immunohistochemistry was applied to detect the expression of COX-2 and NUCB1 in colorectal adenocarcinoma and adjacent tissues." (PMID 37547718, 2023). "The chi-square test result was X2 = 24.79, with a P < 0.005, indicating that NUCB1 was markedly increased in colorectal adenocarcinoma." (PMID 37547718, 2023). "Expressions of COX-2 and NUCB1 in colorectal adenocarcinoma." (PMID 37547718, 2023).
COVID-19 (1 paper, 2024). A disease caused by infection with severe acute respiratory syndrome coronavirus 2. "Nucleobinding 1 (NUCB1) is widely expressed in brain neurons and stabilizes amyloid protofibrils before they mature and become harmful in neurodegenerative diseases; however, its downregulation in our COVID-19 patients suggests decreased neurological protective mechanisms." (PMID 38760690, 2024).
depression (1 paper, 2022). "Understanding the mechanism underlying the interaction between NUCB1 expression and depression in the context of HIV-infection may provide insights that may facilitate the development of a biomarker for diagnosis, new drug target, and treatment response." (PMID 36138887, 2022). "Therefore, we put forward the hypotheses that alterations in NUCB1 expression might be linked to depression among PLWHA." (PMID 36138887, 2022). "Second, there are too little data on NUCB1 levels in CSF from HIV-infected individuals currently suffering from depression to draw a convincing conclusion." (PMID 36138887, 2022). "The mechanism results showing elevated NUCB1 levels in cerebrospinal fluid from HIV-infected patients suffering from depression were confirmed compared to those of HIV-infected patients." (PMID 36138887, 2022). "By combining our experimental results, we propose a schematic presentation of a possible mechanism of NUCB1 involvement in depression in PLWH." (PMID 36138887, 2022). "The results suggest that NUCB1 plays an important role in the pathological processes leading to depression." (PMID 36138887, 2022). "Comparing with only HIV cases, the protein expression of NUCB1 in the CSF was significantly increased in those HIV cases currently suffering from depression." (PMID 36138887, 2022). "Despite all this, this study suggests that the NUCB1 protein may be a novel clinical biomarker for depression, and inhibiting its activity might have a potential function that predicts and monitors responsiveness of treatment." (PMID 36138887, 2022). "Then SHIV-infected rhesus monkeys were used to investigate the possible involvement of the NUCB1 and the CNR1 protein in depression-like behavior." (PMID 36138887, 2022). "Expressions of both nucleobindin 1 (NUCB1) and cannabinoid receptor 1 (CNR1) in the neurons have been found to alter in patients with depressive disorder, but whether it is involved in the development of depression in the context of HIV infection is unknown." (PMID 36138887, 2022). "Furthermore, in 2020, an LC-MS/MS analysis predicted a significantly negative correlation between plasma protein levels of NUCB1 and degree of depression." (PMID 36138887, 2022).
depressive disorder (1 paper, 2022). A melancholy feeling of sadness and despair. "Herein, down-regulation of CNR1 expression and up-regulation of NUCB1 expression in neurons were found in the co-occurrence of depression disorder and SHIV infection, as detected by IHC and Western blot." (PMID 36138887, 2022). "Therefore, NUCB1 inhibition may be considered as a therapeutic agent to relieve depressive disorder." (PMID 36138887, 2022).
Heat Stroke (1 paper, 2020). A condition caused by the failure of body to dissipate heat in an excessively hot environment or during PHYSICAL EXERTION in a hot environment. "HSP-16.1 is localized to the Golgi and functions with PMR-1/PMR1 Ca2+ and Mn2+ transporting ATPase and NUCB-1 to maintain calcium homeostasis under heat stroke." (PMID 33013473, 2020).
lymphoma (1 paper, 2023). A malignant (clonal) proliferation of B- lymphocytes or T- lymphocytes which involves the lymph nodes, bone marrow and/or extranodal sites. "Some of the studies that reported NUCB1 and ANXA5 as up-regulated analyzed the effects of anti-lymphoma drug combinations, such as R-CHOP/CHOP regimens and immunomodulatory agents, on chemo-sensitive or -resistant DLBCL patients’ samples and DLBCL cell lines." (PMID 36611989, 2023).
mental disorder (1 paper, 2022). A disease that has its basis in the disruption of mental process. "In future studies, we will investigate the molecular mechanisms underlying the regulation of NUCB1 expression and the role of NUCB1 in other mental disorders." (PMID 36138887, 2022).
metastatic colorectal cancer (1 paper, 2021). "It is worth noting that a previous report that investigated the functions of non-receptor GEFs in metastatic colorectal cancer found that NUCB1 overexpression was correlated with shorter progression-free survival (PFS)." (PMID 33855021, 2021).
neuroblastoma (1 paper, 2023). Neuroblastoma (NB) is the most common solid, extracranial childhood tumor. "For instance, the overexpression of NUCB1 in neuroblastoma N2a cells is associated with reduced levels of mRNA of the amyloid precursor protein (APP)." (PMID 37047165, 2023).
pancreatic adenocarcinoma (1 paper, 2023). "For instance, METTL3-mediated m6A modification on the 5’UTR of NUCB1 (encoding a calcium-binding protein) mRNA via YTHDF2 (YTH N6-methyladenosine RNA binding protein 2) reader protein in pancreatic adenocarcinoma was associated with poor prognosis." (PMID 36977668, 2023).
cancer (8 papers, 2016 to 2024). A tumor composed of atypical neoplastic, often pleomorphic cells that invade other tissues. "NUCB1 was expressed positively in cancer tissues at a rate of 64.29% (36/56) compared to just 19.64% (11/56) in neighboring tissues." (PMID 37547718, 2023). "For example, the DNA binding domain of NUCB1 can combine with the E-box sequence of the Cripto promoter to activate many intracellular signaling pathways and trigger the biological behavior of cancer cells (Sinha, Pattnaik & Aradhyam, 2019)." (PMID 37547718, 2023). "These endow NUCB1 with important implications in a variety of cellular processes, including autoimmunity, intracellular signaling, osteogenesis, inflammation, and cancer." (PMID 37547718, 2023). "In this study, compared to 19.64% in adjacent tissues, the positive rate of NUCB1 in cancer tissues was significantly increased to 64.29% (P < 0.05), which is consistent with the research results of Sinha, Pattnaik & Aradhyam (2019)." (PMID 37547718, 2023). "The interactions between NUCB1 and the E-box motifs of certain genes involved in tumorigenesis strengthen the hypothesis of NUCB1’s role in cancer progression." (PMID 36611989, 2023). "In vivo and in vitro validation confirmed that overexpressed NUCB1 protein inhibits cell proliferation and by ATF6 regulation, NUCB1 increases drug sensitivity of cancer cells." (PMID 36611989, 2023). "In parallel, we also used another cancer cell line, BXPC-3, which relatively expresses higher levels of NUCB1, to generate stable cells with NUCB1 knockdown." (PMID 33855021, 2021). "Together, these data demonstrate important roles of NUCB1 in suppressing proliferation and enhancing the anti-tumor effects of GEM inpancreatic cancer cells in vitro." (PMID 33855021, 2021). "It was shown that exosomal NUCB1 is involved in the pathophysiology of cancer and participates in EMT and atypical migration in non-tumor cells." (PMID 37047165, 2023). "Prior studies on members of a newly identified family of non-receptor guanine nucleotide exchange factors (GEFs), GIV/Girdin, Daple, NUCB1 and NUCB2 have revealed that GPCR-independent hyperactivation of trimeric G proteins can fuel metastatic progression in a variety of cancers." (PMID 26916336, 2016).